IL10 (interleukin 10)
Diseases named in the same sentence as IL10 in open-access papers (continued):
Sharing a sentence is not in itself a finding about the gene and the disease.
cervical carcinoma (continued). "The seemingly contradictory effects of IL-10 on carcinogenesis might have different implications for HPV infection and cervical cancer, given that angiogenesis is likely to be more important in later development of malignant tumours than in viral infection and persistence." (PMID 28280748, 2017). "The IL-10 high producer phenotypes was more frequent in patients, although this increased frequency was not significant and might be related to an immunosuppressive response and development of HPV-positive cervical cancer." (PMID 23936772, 2013). "We also investigated the levels of the cytokines IL-10, IL-6, TFG-β, and VEGF in serum to examine the claim that the low proportion and impaired maturity of freshly isolated dendritic cell subsets from patients with cervical cancer correlates with increased levels of cytokines in their serum." (PMID 20565840, 2010). "In the future, by locally administering therapeutic cervical cancer vaccines to induce local immune responses, the progression of CIN can be prevented and its regression promoted.The effectiveness of such induction may be evaluated by monitoring changes in local vaginal CD4, CD8, and IL-10 levels." (PMID 41142594, 2025). "IL-4 and IL-10 are expressed in SIL and cervical cancer, but IL-4 is not expressed in normal cervical tissues." (PMID 36726132, 2023).
schizophrenia (91 papers, 2008 to 2025). A major psychotic disorder characterized by abnormalities in the perception or expression of reality. "Our results are supported by those from a study from Al Amsary9 in a Saudi population, in which IL-10 (−1082 G/A) was found to be associated with schizophrenia." (PMID 37868103, 2024). "Previous studies have reported that IL-10 polymorphism at position −1082G is strongly associated with schizophrenia and have demonstrated interethnic differences." (PMID 37868103, 2024). "Dysregulated IL-10 secretion is believed to disrupt the immune response equilibrium and to underlie schizophrenia development." (PMID 37868103, 2024). "The aim of this case-control study was to investigate the association between IL-10 (−1082) G/A gene polymorphisms and schizophrenia among Bataknese, a native tribe inhabiting the North Sumatera province in Indonesia." (PMID 37868103, 2024). "Decreased IL-10 serum levels are considered an underlying mechanism in schizophrenia, because IL-10 participates in the anti-inflammatory response." (PMID 37868103, 2024). "Three biallelic polymorphisms at the promoter region of the interleukin-10 (IL-10) gene have been associated with susceptibility to schizophrenia." (PMID 37868103, 2024). "Only the A allele and AA genotype of the IL-10 gene polymorphism at −1082 G/A contribute to schizophrenia susceptibility in Bataknese." (PMID 37868103, 2024). "An increased risk of schizophrenia has also been implied because of the association between variations of tumor necrosis factor-α and interleukin-10 genes and susceptibility in both CMV infections and schizophrenia." (PMID 37376644, 2023). "The severity of CFS-like symptoms in schizophrenia is associated not only with increased IL-6 but also IL-10 levels." (PMID 35330475, 2022). "It is also important to note that after considering the detrimental effects of the IL-6/IL-23/Th17 axis on the phenome of schizophrenia, IL-10 showed an inverse association with the phenome." (PMID 36256663, 2022). "Regarding the specific immune markers, TNF, a pro-inflammatory cytokine, and IL-10, an anti-inflammatory cytokine, were associated with slowed task performance in patients with schizophrenia." (PMID 32238816, 2020). "In patients with schizophrenia, a significant positive association was identified between antipsychotic dose and both IL-2 (rs = .307, p = 0.040) and IL-10 (rs = .273, p = 0.036)." (PMID 29803226, 2018). "In contrast, a study conducted in antipsychotic-naïve first-episode schizophrenia patients identified decreased IL-10 and IL-1RA associated with 6 weeks of atypical antipsychotic treatment." (PMID 29803226, 2018). "In healthy controls, ErbB activation was associated with a marked production of IL-10, which was dampened in schizophrenia." (PMID 28646138, 2017). "The most important result of this study is that the level of TGF-β1, IL-23 and IL-10 were independently associated with plasma levels of S100B in patents with schizophrenia." (PMID 27279465, 2016). "IL10, as an important immunoregulatory cytokine, is located on a region reported to be related to schizophrenia in genetic association studies." (PMID 23951054, 2013). "Some polymorphisms on IL10 gene are associated with susceptibility to the development of schizophrenia." (PMID 23951054, 2013). "This study also describes for the first time the association of IL-10 gene promoter ATA/ATA low IL-10 producing genotype linked to schizophrenia in Spanish females." (PMID 21658228, 2011). "Haplotype GCC of three IL-10 promoter SNPs was firstly identified for a significantly association with schizophrenia in Caucasians, then similar results also replicated in Chinese cohort." (PMID 23675088, 2008). "Second, the interaction between DRD4 and the IL-10 polymorphism in schizophrenia was further investigated." (PMID 23675088, 2008).
schizophrenia (continued). "Among three promoter SNPs of IL-10, other than -1082G/A polymorphism, another work done by analyzed Chinese ethnic samples conclude that -592A allele was associated with schizophrenia as well." (PMID 23675088, 2008). "The purpose of this study was explored the association between the -1082G/A, -819T/C, and -592C/A polymorphisms of interleukin-10 (IL-10) in schizophrenia." (PMID 23675088, 2008). "Therefore, in this study, we aimed to investigate IL-10 gene polymorphism, specifically, at −1082 G/A, and associations with schizophrenia susceptibility in Bataknese." (PMID 37868103, 2024). "Decreased glutamatergic neurotransmission may be associated with altered transport of synaptic vesicles associated with the concentration level of IL-10 in the brain of patients with schizophrenia." (PMID 35163141, 2022). "While the overexpression of IL-10 in the absence of an inflammatory insult was linked with deficits in spatial and associative learning, transgenic overexpression of IL-10 in the late pregnancy UIA model reduced the development of schizophrenia-like behavioral abnormalities." (PMID 35215136, 2022). "In schizophrenia, elevated peripheral IL-10 levels were associated with the loss of microstructural white matter integrity, supporting the opinion that inflammation is associated with schizophrenia playing a key role in the pathology of microstructural white matter." (PMID 33746786, 2021). "Serum IL-10 levels were also associated with the severity of symptoms in schizophrenia patients." (PMID 32341334, 2020). "Third, the cross-sectional nature of our study was limited to determine whether there is a causative relationship between peripheral IL-10 and the alterations of WM integrity in schizophrenia." (PMID 30792621, 2019). "The aim of this study was to explore whether peripheral IL-10 was associated with microstructural WM integrity in schizophrenia." (PMID 30792621, 2019). "Growing evidence has demonstrated that IL-10 is associated with schizophrenia." (PMID 30792621, 2019). "Thus, the aims of this study were to verify the linkage of the IL-10 gene promoter SNPs and haplotypes with schizophrenia and to explore a putative sex-specific genetic association of these polymorphisms in a Spanish schizophrenic population." (PMID 21658228, 2011). "This study addresses the significant association of IL-10 -1082A allele with schizophrenia females." (PMID 21658228, 2011). "Hence, the first purpose of the present study was to explore the role of the -1082G/A, -819T/C, and -592C/A polymorphisms of IL-10 in schizophrenia." (PMID 23675088, 2008). "In addition, the persons who carry haplotype ACA of IL-10 promoter SNPs were estimated for 5.789 fold higher risk to develop schizophrenia than controls." (PMID 23675088, 2008). "Additionally, studies have shown that elevated prenatal levels of IL-10 and other Th2/anti-inflammatory cytokines in maternal blood may have a protective effect on offspring, reducing the risk of developing schizophrenia." (PMID 41008291, 2025). "Increased IL-10 has been linked to atypical antipsychotic treatment in mouse models exposed to lipopolysaccharide (LPS) and polyinsinic-polycytidylic acid (Poly I:C), as well as in vitro studies using Poly I:C stimulated blood samples from patients with schizophrenia." (PMID 29803226, 2018). "Thus, we highly suspect that individual who carry haplotype ACA of IL-10 promoter SNPs (-1082A, -819C, -592A) might be at higher risk to develop schizophrenia later in their life." (PMID 23675088, 2008). "Activation of STAT1 is downstream of cytokine receptors that signal from specific pro-inflammatory cytokines known to be dysregulated in schizophrenia, such as IFNγ, IL-6, IL-2, and IL-10." (PMID 40259965, 2025). "Increased concentrations of IL-1β, IL-6, IL-10, IL-17, sIL-2R, and IL-33, but also decreased concentrations of TNF-α, were similarly associated with more severe positive symptoms of schizophrenia." (PMID 40364201, 2025).
schizophrenia (continued). "These mixed findings highlight the complex role of IL‐10 in schizophrenia and the need for further research to clarify its effects." (PMID 40159715, 2025). "Polymorphisms in immune-related genes, including TNF-α, interleukin-10 (IL-10), and complement C4, have been correlated with increased susceptibility to CMV and increased probability of schizophrenia, suggesting shared pathways in disease aetiology." (PMID 40806558, 2025). "Earlier findings have revealed that a significant association exists between an increase in the PANSS score (exacerbation of schizophrenia symptoms) and higher concentrations of IL-17 and IL-10." (PMID 40364201, 2025). "Schizophrenia is associated with elevated levels of IL-6, IL-8, and TNF-α and reductions in the anti-inflammatory IL-10." (PMID 38673018, 2024). "Increased IL-10 levels have also been reported in patients with chronic schizophrenia treated with risperidone or clozapine for at least 6 weeks." (PMID 39595201, 2024). "A decrease in the IL-10/IL-6 ratio also confirms the activation of pro-inflammatory processes in schizophrenia." (PMID 37239308, 2023). "Polymorphic variants of the IL1B, IL6, IL6R, IL10, IL17A, and TNFA genes have been associated with schizophrenia." (PMID 37510364, 2023). "Significantly higher levels of the pro-inflammatory cytokine IL-6 and lower levels of the anti-inflammatory IL-10 have been found in patients with schizophrenia, indicating a pro-inflammatory state." (PMID 37239308, 2023). "On the flip side, studies on peripheral blood show downregulation of tlr3 and 5 mRNA levels and upregulation of il6 and il10 mRNA levels in patients with schizophrenia, which is in contrast to evidence from brain samples." (PMID 37627253, 2023). "Atypical neuroleptics, such as risperidone, reduced serum IL-6 in schizophrenia patients, along with reducing IL-10 and TNF-α in first episode patients, which also coincided with the results of our study." (PMID 37189796, 2023). "Proteomic and inflammation alterations (such as neurotrophins, IL-10, and glutathione peroxidase) combined with ML technologies were able to distinguish healthy controls from patients with bipolar disorders or schizophrenia." (PMID 36399236, 2022). "Data regarding the levels of IL-10 in patients with schizophrenia are mixed; they have been reported to be higher and lower in first-episode patients than in controls." (PMID 35887634, 2022). "In patients with a duration of schizophrenia of 10 years or more, the level of IL-10 was higher than that in patients with a disease duration of 5 years or less (p = 0.042)." (PMID 36556337, 2022). "Some studies indicate that subjects with schizophrenia exhibited a significant decrease in IL-10 levels in comparison to healthy volunteers." (PMID 35782435, 2022). "Males with schizophrenia had statistically significantly higher levels of IL-10 (p = 0.017), IL-5 (p = 0.048), and TNF-α (p = 0.025) than did healthy age-matched males." (PMID 36556337, 2022). "In the present study, we recruited a relatively larger sample of patients with schizophrenia and measured more plasma inflammatory cytokines, including IL-1β, IL-2, IL-4, IL-6, IL-8, IL-10, IL-12, IL-17, TNF-α, IFN-γ, and CRP." (PMID 36341400, 2022). "Increments in cytokines such as IL-1β, TNF-α, IL-6, and IL-10 have frequently been described in schizophrenia." (PMID 36256663, 2022). "In this work, we found significantly higher serum levels of proinflammatory (IFN-γ, IL-5, IL-6, IL-8, IL-15, and TNF-α) and anti-inflammatory (TGF-α, IL-10, and IL-1RA) cytokines in patients with schizophrenia than in healthy individuals." (PMID 36556337, 2022). "Following on from these findings regarding the role of immune processes in schizophrenia development the present study evaluates the serum levels of anti-inflammatory cytokine IL-10, and pro-inflammatory chemokines CXCL8 and CX3CL1 in schizophrenic patients." (PMID 35782435, 2022).
schizophrenia (continued). "Data from 62 studies, analyzed IFN-γ, IL-4, IL-2, soluble IL-2 receptor (sIL-2R), IL-1β, IL-1 receptor antagonist (IL-1RA), TNF-α, IL-6, soluble IL-6 receptor (sIL-6R), and IL-10 in schizophrenia." (PMID 33746786, 2021). "Studies performed to understand the relationship between IL-10 and schizophrenia have provided contradictory results." (PMID 33746786, 2021). "IL-2, IL-6, IL-10 are known markers of immune status in schizophrenia; and the alterations of their levels are connected with the severity of clinical symptoms and potential clinical implications." (PMID 34025476, 2021). "In schizophrenia patients, significant interactive effects of genotypes of COMT and IL-10 were seen, and the COMT rs4680 variant was associated with tardive dyskinesia." (PMID 34725583, 2021). "Blood samples from the Zip8+/− mice, collected after LPS treatment, displayed higher levels of several cytokines, including IL-6 and IL-10, which have been shown to be elevated in schizophrenia." (PMID 33608496, 2021). "In the present study, we found that schizophrenia patients with olanzapine or clozapine monotherapy exhibited increased plasma levels of IL-6, IL-10, and TNF-α, which was also observed in many previous studies." (PMID 33324265, 2020). "A recent study compared TSPO PET of schizophrenia patients and controls with combined peripheral and CSF measures of IL1β, IFNγ, IL-10, IL-6 and TNF-α." (PMID 32179746, 2020). "This study reveals, for the first time, the involvement of innate type 17 immune response, besides acquired, as well as the predomination of proinflammatory IL-17 over anti-inflammatory IL-10 in the peripheral blood of patients with schizophrenia in remission." (PMID 33182582, 2020). "Previously, levels of IFN-γ, IL-10 and TGF-β have been reported to be associated with aggression in schizophrenia patients." (PMID 31509578, 2019). "Our study found that by adjusting for IL-10, a widespread FA/AD reduction and MD/RD increase in schizophrenia patients compared with controls." (PMID 30792621, 2019). "One study on Polish schizophrenia patients detected a functional polymorphism in the proinflammatory cytokine IL-6 and the anti-inflammatory cytokine IL-10 genes in patients with paranoid schizophrenia." (PMID 31405205, 2019). "Interleukin 10 (IL-10) has been proven to be related to schizophrenia in both animal and human models." (PMID 30792621, 2019). "It therefore provides novel information about the role of cytokines, especially IL-10 in the neuropathology of schizophrenia and adds more evidence relevant to the neuroinflammatory model of schizophrenia." (PMID 30792621, 2019). "The levels of serum IL-10 were higher in patients than in controls (schizophrenia: 10.59 ± 0.24 pg/ml; controls: 9.27 ± 0.24 pg/ml, p < 0.001)." (PMID 30792621, 2019). "Changes in cytokine levels were also associated with antipsychotic medication, such that higher IL-2 and IL-10 levels were related to higher antipsychotic doses at the time of the scan in the schizophrenia sample." (PMID 29803226, 2018). "Taken together, these results show a strong pro-inflammatory phenotype in the serum of individuals with schizophrenia compared to controls, with bipolar participants characterized by nonsignificant pro-inflammatory elevations and uniquely elevated IL-10." (PMID 29803226, 2018). "For example, Sobis and colleagues treated 17 chronic schizophrenia patients with aripiprazole over 1 month and identified significant reductions in a range of pro-inflammatory cytokines with a sole increase in IL-10." (PMID 29803226, 2018). "Clozapine has previously been shown to decrease production of IFN-γ and enhance IL-4 and IL-10 in poly (I:C)-stimulated PBMC cultures from schizophrenia patients, which suggests an effect on CD4+ T cell differentiation." (PMID 28356108, 2017). "In contrast, IL-10 response was significantly dampened in schizophrenia as compared to the control values (p < 0.01)." (PMID 28646138, 2017).